RNU7-12P (RNA, U7 small nuclear 12 pseudogene)
Synonyms: U7.12; RNU7-100P
Gene: Small nuclear RNA gene on chromosome 10 (27,232,255 to 27,232,316, reverse strand). Ensembl gene ENSG00000251839.
Homologues: Orthologues: chimpanzee U7 (98% identical), macaque U7 (97% identical). Paralogues in human: RNU7-19P (89% identical), RNU7-35P (89% identical), RNU7-1 (87% identical), RNU7-13P (87% identical), RNU7-25P (87% identical), RNU7-2P (87% identical), RNU7-52P (87% identical), RNU7-6P (87% identical), RNU7-7P (87% identical), RNU7-11P (85% identical), RNU7-18P (85% identical), RNU7-20P (85% identical), and 142 more.